SEC61B (SEC61 translocon subunit beta)
Description:
Component of SEC61 channel-forming translocon complex that mediates transport of signal peptide-containing precursor polypeptides across the endoplasmic reticulum (ER). Forms a ribosome receptor and a gated pore in the ER membrane, both functions required for cotranslational translocation of nascent polypeptides. The SEC61 channel is also involved in ER membrane insertion of transmembrane proteins: it mediates membrane insertion of the first few transmembrane segments of proteins, while insertion of subsequent transmembrane regions of multi-pass membrane proteins is mediated by the multi-pass translocon (MPT) complex. The SEC61 channel cooperates with the translocating protein TRAM1 to import nascent proteins into the ER.
Tractability: Small molecule: a structure with a bound ligand is known. Antibody: UniProt predicts a signal peptide or a membrane-spanning region. PROTAC: ubiquitination databases record sites on it; its protein half-life has been measured.
Gene: Protein-coding gene on chromosome 9 (99,222,064 to 99,230,615, forward strand). Ensembl gene ENSG00000106803.
Subcellular location: Endoplasmic reticulum membrane
Subcellular location (Human Protein Atlas): Endoplasmic reticulum
Pathways (Reactome):
Immune System: ER-Phagosome pathway
Metabolism of proteins: SRP-dependent cotranslational protein targeting to membrane
Protein localization: Insertion of tail-anchored proteins into the endoplasmic reticulum membrane
Gene Ontology:
Molecular function: epidermal growth factor binding; protein binding; ribosome binding; RNA binding; guanyl-nucleotide exchange factor activity
Biological process: ERAD pathway; retrograde protein transport, ER to cytosol; SRP-dependent cotranslational protein targeting to membrane, translocation; post-translational protein targeting to membrane, translocation; intracellular protein transport
Cellular component: endoplasmic reticulum; endoplasmic reticulum membrane; endoplasmic reticulum quality control compartment; membrane; Sec61 translocon complex; cytosol; endoplasmic reticulum Sec complex
Genetic constraint (gnomAD): Loss-of-function variants: 5 observed, 7.5 expected, observed/expected ratio (o/e) 0.67, 90% interval 0.35 to 1.39. That is too few expected variants to judge how well the gene tolerates losing a copy. Missense variants: 82 observed, 81.31 expected, observed/expected ratio (o/e) 1.01, 90% interval 0.84 to 1.21. Synonymous variants: 44 observed, 31.13 expected, observed/expected ratio (o/e) 1.41, 90% interval 1.11 to 1.8.
Homologues: Orthologues: chimpanzee SEC61B (100% identical), macaque SEC61B (100% identical), guinea pig SEC61B (99% identical), mouse Sec61b (99% identical), pig SEC61B (99% identical), rat Sec61b (99% identical), zebrafish sec61b (81% identical), Drosophila melanogaster Sec61beta (71% identical), Caenorhabditis elegans sec-61.B (51% identical).
Diseases named in the same sentence as SEC61B in open-access papers:
SEC61B is named in the same sentence as 21 diseases in open-access papers, as found by Europe PMC text mining. Sharing a sentence is not in itself a finding about the gene and the disease. The quoted sentences say what the papers report.
atherosclerosis (2 papers, 2011 to 2022). A disease characterized by the build-up of fatty material and calcium deposition in the arterial wall resulting in partial or complete occlusion of the arterial lumen. "One studies have shown that after in vitro and in vivo injection of endotoxin and LPS, six candidate genes (BATF, BID, C3aR1, IL1RN, SEC61B and SLC43A3) were identified to be associated with inflammation and atherosclerosis." (PMID 36303246, 2022). "The role of BID, SEC61B, SLC43A3 in atherosclerosis is not yet established." (PMID 21827714, 2011).
diabetes (2 papers, 2025). "Dissecting the molecular mechanisms linking ER stress to upregulated SEC61B may also identify additional therapeutic targets for preventing thrombosis in diabetes and other chronic conditions associated with ER stress." (PMID 40829178, 2025). "Given SEC61’s role as a calcium leak channel in nucleated cells, we propose that SEC61B contributes to calcium dysregulation in diabetes." (PMID 40829182, 2025). "In this issue of the JCI, Kong and colleagues used an unbiased proteomic approach to identify elevated SEC61B in platelets from patients with diabetes and from hyperglycemic mice." (PMID 40829178, 2025). "Functionally, increased SEC61B was associated with increased cytosolic calcium, while SEC61 inhibition decreased calcium leak and platelet aggregation, implicating SEC61B in platelet hyperreactivity in diabetes." (PMID 40829182, 2025). "Importantly, the authors validated their initial findings by observing increased SEC61B in platelets from a second cohort of patients with diabetes as well as in platelets and megakaryocytes from mice with hyperglycemia." (PMID 40829178, 2025). "Upregulation of SEC61B contributes to platelet hyperreactivity in diabetes." (PMID 40829182, 2025).
glioma (2 papers, 2022 to 2025). A benign or malignant brain and spinal cord tumor that arises from glial cells (astrocytes, oligodendrocytes, ependymal cells). "Here, we identified a novel ER stress and UPR-driven gene signature, ESURATAG, composed of six genes (DERL2, RPN2, SEC13, SEC61A1, SEC61B, and STT3A) that are significantly upregulated in gliomas from older patients and strongly linked to tumor aggressiveness." (PMID 40718795, 2025). "Six out of eight genes namely, DERL2, RPN2, SEC13, SEC61A1, SEC61B and STT3A were interacting, and were combined into ER stress and UPR-driven aging-related tumor aggressiveness in glioma (ESURATAG) gene signature." (PMID 40718795, 2025). "We identified ER stress and UPR as key aging-related mechanism behind tumor aggressiveness in gliomas, and developed a six gene “ER Stress and UPR-driven Aging-related Tumor Aggressiveness in Glioma” (ESURATAG) gene signature, comprising DERL2, RPN2, SEC13, SEC61A1, SEC61B, and STT3A." (PMID 40718795, 2025).
Hyperglycemia (2 papers, 2025). An increased concentration of glucose in the blood. "We sought to determine if increased platelet SEC61B in hyperglycemia is associated with increased calcium leak." (PMID 40829182, 2025). "SEC61B upregulation seems to be a bone fide hyperglycemia phenomenon, as we confirmed SEC61B upregulation in a separate human diabetic cohort and in STZ-induced hyperglycemic mice." (PMID 40829182, 2025). "Mechanistically, it remains to be determined how hyperglycemia and ER stress lead to increased SEC61B expression in platelets." (PMID 40829178, 2025). "We identified that SEC61 translocon subunit β (SEC61B) was increased in platelets from humans and mice with hyperglycemia and in megakaryocytes from mice with hyperglycemia." (PMID 40829182, 2025). "To understand if upregulation of platelet SEC61B in hyperglycemia originates from megakaryocytes, we employed two additional mouse models of type 2 diabetes, available to us, for analysis of megakaryocyte SEC61B content." (PMID 40829182, 2025). "SEC61B upregulation likely occurs secondary to platelet ER stress in hyperglycemia, as SEC61B was also upregulated following chemical induction of ER stress." (PMID 40829182, 2025). "Our most important finding was increased platelet SEC61B in hyperglycemia." (PMID 40829182, 2025). "SEC61B is increased in conditions of hyperglycemia and ER stress." (PMID 40829182, 2025). "Increase of SEC61B in hyperglycemia originates at the megakaryocyte level." (PMID 40829182, 2025). "SEC61B is a hyperglycemia-responsive regulator of calcium flux in platelets." (PMID 40829182, 2025).
ZIKV infection (2 papers, 2018 to 2024). "Upon ZIKV infection, both calnexin and SEC61B were aggregated around the nuclei and co-localized with ZIKV E protein in the control cells, while SUN2 KO significantly dampened their aggregation." (PMID 38177122, 2024).
autosomal dominant polycystic liver disease (1 paper, 2022). An autosomal dominant inherited condition characterized by many cysts of various sizes scattered throughout the liver. "Autosomal Dominant Polycystic Liver Disease (ADPLD) leads to PLD only and is caused by a mutation in PRKCSH, SEC63, LRP5, ALG8 or SEC61B." (PMID 35216547, 2022).
colorectal cancer (1 paper, 2019). A primary or metastatic malignant neoplasm that affects the colon or rectum. "Furthermore, in colorectal cancer, curcumin can modulate gene expression of HSPA5, SEC61B, G6PD, HMOX1, and PDE3B, affecting essential pathways like DNA replication or the cell cycle." (PMID 31744117, 2019).
common variable immunodeficiency (1 paper, 2023). "The diseases include SEC61A1-linked common variable immunodeficiency, neutropenia and tubulointerstitial kidney disease, SEC61B- and SEC63-linked polycystic liver disease, and TRAP-, as well as TRC35-, TRC40-, and CAML-linked congenital disorders of glycosylation." (PMID 37762469, 2023).
coronary artery disease (1 paper, 2025). "We found that only SEC61B had a significant positive correlation with serum fructosamine; which was independent of both scores used to assess coronary artery disease burden: SYNTAX (Spearman’s rho –0.011, P = 0.95) and Gensini (Spearman’s rho –0.064, P = 0.69)." (PMID 40829182, 2025).
myelogenous leukemia (1 paper, 2024). "The suppression of SEC61A1 and SEC61B has been observed to stimulate Ddit3 expression in myelogenous leukemia cells." (PMID 39000233, 2024).
tumor (3 papers, 2018 to 2025). "To investigate if ITPN allows the simultaneous generation of biallelic knock-ins carrying different fluorescent tags within each allele, we targeted the SEC61B, MAP4, and HIST1H2BC loci in tumor organoids with both mNeongreen and mScarlet targeting vectors." (PMID 35089911, 2022). "Finally, we compared the efficiency of an N-terminal mScarlet knock-in at the SEC61B locus between tumor and normal colon organoids." (PMID 35089911, 2022). "The anti-tumor response to the combination of curcumin and OPCs in mice xenograft tumors and organoids derived from primary human CRC tumors correlated with the altered gene expressions of HSPA5, IHH, PDE3B, cyclin D1 and SEC61B." (PMID 30218018, 2018).
SEC61B also shares sentences with these, for which no sentence is quoted: cancer (2 papers); congenital disorder of glycosylation (1); cyst (1); cystic kidney disease (1); Kidney Cyst (1); neutropenia (1); polycystic kidney disease (1); polycystic liver disease (1); tubulointerstitial kidney disease (1); type 2 diabetes (1).